RPL10 (ribosomal protein L10)
Description:
Component of the large ribosomal subunit. Plays a role in the formation of actively translating ribosomes. May play a role in the embryonic brain development.
Synonyms: DXS648E; QM; NOV; DXS648; FLJ23544; L10; uL16; AUTSX5; MRXS35
Tractability: Small molecule: an approved drug acts on it; a structure with a bound ligand is known; a high-quality ligand is known. PROTAC: UniProt records ubiquitination sites on it; ubiquitination databases record sites on it; its protein half-life has been measured; a small molecule that binds it is known. Other modalities: a drug acting on it is in phase 2 or 3 trials.
Target class: Other cytosolic protein
Gene: Protein-coding gene on chromosome X (154,389,955 to 154,409,168, forward strand). Ensembl gene ENSG00000147403.
Subcellular location: Cytoplasm
Subcellular location (Human Protein Atlas): Cytosol; Endoplasmic reticulum
Pathways (Reactome):
Metabolism of proteins: Eukaryotic Translation Termination; Formation of a pool of free 40S subunits; GTP hydrolysis and joining of the 60S ribosomal subunit; L13a-mediated translational silencing of Ceruloplasmin expression; PELO:HBS1L and ABCE1 dissociate a ribosome on a non-stop mRNA; Peptide chain elongation; Ribosome Quality Control (RQC) complex extracts and degrades nascent peptide; SRP-dependent cotranslational protein targeting to membrane; ZNF598 and the Ribosome-associated Quality Trigger (RQT) complex dissociate a ribosome stalled on a no-go mRNA
Metabolism of RNA: Major pathway of rRNA processing in the nucleolus and cytosol; Nonsense Mediated Decay (NMD) enhanced by the Exon Junction Complex (EJC); Nonsense Mediated Decay (NMD) independent of the Exon Junction Complex (EJC)
Cellular responses to stimuli: Response of EIF2AK4 (GCN2) to amino acid deficiency
Developmental Biology: Regulation of expression of SLITs and ROBOs
Disease: Viral mRNA Translation
Metabolism: Selenocysteine synthesis
Gene Ontology:
Molecular function: protein binding; RNA binding; structural constituent of ribosome; translation regulator activity
Biological process: cytoplasmic translation; embryonic brain development; intracellular signal transduction; negative regulation of transcription by RNA polymerase II; negative regulation of myoblast fusion; striated muscle contraction; translation; regulation of translation
Cellular component: cytosol; cytosolic large ribosomal subunit; cytosolic ribosome; endoplasmic reticulum; membrane; nucleus; protein-containing complex; smooth endoplasmic reticulum; cytoplasm; ribosome
Gene-disease validity (ClinGen):
ClinGen rates the evidence that RPL10 causes each of these diseases.
X-linked syndromic intellectual disability (X-linked): Definitive.
Cancer hallmarks: proliferative signalling (promotes); change of cellular energetics; escaping programmed cell death (promotes); invasion and metastasis (promotes)
Homologues: Orthologues: mouse Rpl10 (99% identical), tropical clawed frog rpl10 (96% identical), zebrafish rpl10 (92% identical), Drosophila melanogaster RpL10 (78% identical), Caenorhabditis elegans rpl-10 (73% identical). Paralogues in human: RPL10L (96% identical).
Diseases named in the same sentence as RPL10 in open-access papers:
RPL10 is named in the same sentence as 59 diseases in open-access papers, as found by Europe PMC text mining. Sharing a sentence is not in itself a finding about the gene and the disease. The quoted sentences say what the papers report.
T-cell acute lymphoblastic leukemia (14 papers, 2014 to 2025). Acute lymphoblastic leukemia of T-cell origin. "For example, recurrent somatic mutations in the RPL10 gene (encoding the ribosomal protein uL16) have been identified in 10% of cases of paediatric T-cell acute lymphoblastic leukaemia (T-ALL)." (PMID 31115337, 2019). "Here, we integrate mRNA sequencing, ribosome footprinting, polysomal RNA sequencing and mass spectrometry datasets from a mouse lymphoid cell model to characterize the T-cell acute lymphoblastic leukemia (T-ALL) associated ribosomal RPL10 R98S mutation." (PMID 31186416, 2019). "In this regard, it is interesting that frequent mutations in RPL5 and RPL10 or in CNOT3 have been observed to accumulate in adult T-cell acute lymphoblastic leukemia (T-ALL)." (PMID 28588606, 2017). "Mutations in the ribosomal protein Rpl10 (uL16) can be drivers of T-cell acute lymphoblastic leukemia (T-ALL)." (PMID 28715419, 2017). "Mutations in RPL10 were identified as driver-mutations in pediatric T-cell acute lymphoblastic leukemia (T-ALL)." (PMID 28715419, 2017). "The biomedical importance of the rpL10 loop was recently highlighted by the discovery that a significant fraction of T-cell acute lymphoblastic leukemia patients harbor mutations of R98, and in one patient at Q123, both of which lie at the base of the loop." (PMID 24214990, 2014). "It was also reported that R98S mutation in RPL10 associated with pediatric T-cell acute lymphoblastic leukemia (T-ALL) generates specialized ribosomes that increase IRES-dependent translation of antiapoptotic factor BCL-2 thereby increasing leukemic cell survival." (PMID 36806717, 2023). "The ribosomal protein RPL10 is frequently mutated in T-cell acute lymphoblastic leukemia (T-ALL)." (PMID 31186416, 2019). "However, the translation of BCL-2 could be specifically compensated by IRES activation, as researchers have reported that IRES-dependent BCL-2 contributed to the malignant element of RPL10 R98S mutation in pediatric T-cell acute lymphoblastic leukemia." (PMID 36365147, 2022). "Variants or dysregulation of RPL10 have been linked to neurodevelopmental disorders, such as MRXS35 (OMIM#300998) and AUTSX5 (OMIM#300847), as well as certain cancers, including T-cell acute lymphoblastic leukemia (T-ALL) and multiple myeloma." (PMID 40861044, 2025). "There is one report implicating RPL10 in T cell acute lymphoblastic leukemia (T-ALLs)." (PMID 30479569, 2018). "In addition, recurring mutations in RPL10 are associated with pediatric T-cell acute lymphoblastic leukemia (T-ALL) in humans, with the most commonly identified mutation being rpl10-R98S." (PMID 28715419, 2017).
acute lymphoblastic leukemia (12 papers, 2017 to 2025). Leukemia with an acute onset, characterized by the presence of lymphoblasts in the bone marrow and the peripheral blood. "Exome sequencing revealed mutations in CNOT3 and the ribosomal genes RPL5 and RPL10 in acute lymphoblastic leukemia." (PMID 36147491, 2022). "The R98S mutation in Rpl10 (uL16), which is present in 7.9% of pediatric T-cell acute lymphoblastic leukemia (T-ALL) cases, has been shown to influence Jak-Stat signaling." (PMID 38989007, 2024). "Sertraline selectively inhibited the proliferation of serine synthesis dependent breast cancer, RPL10 R98S T-cell acute lymphoblastic leukemia (T-ALL) cells, and NKX2-1 T-ALL and NSCLC cells." (PMID 38160212, 2024). "Moreover, mutations in the essential internal loop of Rpl10 (uL16) are found in ∼8% of pediatric T-cell acute lymphoblastic leukemia (T-ALL) patients, with Rpl10_R98S being the most common." (PMID 36790396, 2023). "Indeed, mutations in CNOT3, the ortholog of Not5, or in the RPL5 and RPL10 ribosomal proteins, are associated with adult T-cell acute lymphoblastic leukemia (T-ALL)." (PMID 28588606, 2017). "Although RPL10 contribution to cancer was initially proposed almost 30 years ago, this issue has been intensely studied only in the past decade, after mutations in its sequence were described in the context of pediatric T-cell acute lymphoblastic leukemia (T-ALL)." (PMID 33227977, 2020).
pancreatic cancer (12 papers, 2017 to 2025). "UFMylation of ribosomal protein L10 (RPL10)in pancreatic cancer tissues enhances cell proliferation and promotes cancer cell stemness by upregulating Krüppel-like factor 4 (KLF4) expression." (PMID 41179291, 2025). "In pancreatic cancer cells, ribosomal protein Rpl10 (uL16) has been identified as a regulator of mitochondrial ROS levels." (PMID 38271612, 2024). "Overall, UFMylation of RPL10 is a crucial process that promotes the stemness of pancreatic cancer cells, contributing to the progression of pancreatic cancer." (PMID 39247188, 2024). "In summary, we have confirmed the ufmylation of RPL10 in pancreatic cancer cells, xenografted tumor tissues as well as tumor tissues from PAAD patients." (PMID 37280198, 2023). "Previously, using dimethyl-amino-parthenolide (DMAPT) as a molecular probe, we found that DMAPT can directly bind RPL10 and synergistically exhibit its anti-proliferative activity from the inhibition of p65 in pancreatic cancer cells." (PMID 37280198, 2023). "To ensure the association between RPL10 ufmylation and PAAD with clinical relevance, we first determined the specificity of RPL10 ufmylation in pancreatic cancer cell lines." (PMID 37280198, 2023). "RPL10 ufmylation was clearly observed in pancreatic cancer cells, whereas another ribosomal protein, RPS3, was unable to be modified by UFM1." (PMID 37280198, 2023). "In our previous study, RPL10 was also found to regulate IKKγ and p65 for inhibiting the proliferation of pancreatic cancer cells." (PMID 37280198, 2023). "Wild-type RPL10 (uL16) has also been described to regulate the expression of proteins related to ROS production and to control mitochondrial ROS production in pancreatic cancer." (PMID 30862070, 2019). "Although more detailed mechanistic study on the involvement of ROS regulation and the relationship with pancreatic cancer progression is required, current evidence clearly supports the roles of RPL10 in the regulation of ROS level in the cancer cells." (PMID 30172100, 2018). "Although current evidence directs the roles of extra-ribosomal RPL10 to carcinogenesis and cancer development, how RPL10 functions its tumorigenic potential in pancreatic cancer cells remains largely unclear." (PMID 30172100, 2018). "The difference of mitochondrial ROS level from RPL10 alteration strongly indicated a regulatory role of RPL10 on ROS level in mitochondria, suggesting that a proper expression of RPL10 is essential for maintaining ROS level in pancreatic cancer cells." (PMID 30172100, 2018). "When RPL10 was knocked-down in PANC-1 and MIA PaCa-2 cells, the expression of OSGIN1 indeed markedly increased, whereas HMOX1 showed little change in both cells, indicating that RPL10 is possible to regulate ROS level in pancreatic cancer cells." (PMID 30172100, 2018). "RPS11 and RPS20 have been proposed as prognostic markers in glioblastoma and the down-regulation of RPL10 correlates with altered treatment response to dimethylaminoparthenolide (DMAPT) in pancreatic cancer." (PMID 29530001, 2018). "Previously, ribosomal protein L10 (RPL10) was suggested to possess extra-ribosomal functions in pancreatic cancer cells in addition to being proposed as a tumor suppressor or transcription co-regulator." (PMID 30172100, 2018). "In conclusion, we have employed chemical proteomics approach to reveal the specific and direct interaction between DMAPT and RPL10 after confirming the anti-proliferative effects of DMAPT in pancreatic cancer cell lines." (PMID 28388532, 2017). "Together, the present study strongly implies that RPL10 is a novel target with therapeutic potential for the treatment of pancreatic cancer." (PMID 28388532, 2017). "Meanwhile, the expression profiles of RPL10 in these pancreatic cancer cell lines were detected by Western blotting." (PMID 28388532, 2017).
pancreatic cancer (continued). "Additionally, in pancreatic cancer, UFMylation of ribosomal protein RPL10 has been found to significantly facilitate the proliferation and stemness of tumour cells." (PMID 39259506, 2024). "The ufmylation of RPL10 was found in both pancreatic cancer cells and tissues." (PMID 39247188, 2024). "Additionally, the decrease of RPL10 ufmylation inhibited pancreatic cancer cell proliferation and stemness." (PMID 37280198, 2023). "Finally, mutagenesis of the specific sites of ufmylation in RPL10 impeded the proliferation and stemness of pancreatic cancer cells." (PMID 37280198, 2023). "Previously, in addition to the close relationship between RPL10 R98S mutation and leukemia, the expression of PRL10 has been indicated to affect the development of various cancers, including prostate cancer, ovarian cancer and pancreatic cancer." (PMID 37280198, 2023). "Therefore, we knocked down E3 ligase UFL1 to evaluate the changes of RPL10 ufmylation, proliferation and stemness-related characteristic features in pancreatic cancer cells." (PMID 37280198, 2023). "Additionally, RPL10 functioned as a buffering molecule to balance and regulate ROS level in mitochondrion of pancreatic cancer cells." (PMID 37280198, 2023). "To ascertain the modification sites for biochemical dissection of the functions of RPL10 ufmylation in pancreatic cancer cells, we overexpressed RPL10-K30R/K101R mutants to examine the changes of RPL10 ufmylation after the elimination of potential interferences from endogenous RPL10." (PMID 37280198, 2023). "Through participating in ATP production and influencing Complex I activity in mitochondria, RPL10 could affect the expression of redox related proteins to regulate ROS balance and cellular processes in pancreatic cancer cells." (PMID 30172100, 2018). "Together, the present study suggests that the regulation of ROS level by mitochondrial RPL10 is one of the major extra-ribosomal functions in pancreatic cancer cells, which could be used as an indicator for the tumorigenesis of pancreatic cancer." (PMID 30172100, 2018). "In terms of pancreatic cancer, the potential target of RPL10 for the treatment of this disease may relate to the extraribosomal functions as the autogenous regulation of translation." (PMID 28388532, 2017). "Thus, the expression of RPL10 seemed to show a positive correlation to the inhibitory activity of DMAPT against various pancreatic cancer cells." (PMID 28388532, 2017). "Because RPL10 ufmylation was associated with PAAD development and originally reported in E14 embryotic stem cells, it was reasonable for us to hypothesize that RPL10 ufmylation might be related to the proliferation and stemness of pancreatic cancer cells for tumor development." (PMID 37280198, 2023). "To elucidate the process of RPL10 ufmylation involved in pancreatic cancer cells, we used immunoprecipitation to examine the interactions between co-substrates RPL10 and UFM1 as well as between RPL10 and E3 ligase UFL1, which could be similar to the ufmylating modifications of ASC1 and RPL26." (PMID 37280198, 2023). "Given the various extra-ribosomal functions of RPL10 and the necessary roles of mitochondria in the redox-system, it is natural and reasonable to explore whether RPL10 directly participates in the mitochondrial events in pancreatic cancer cells." (PMID 30172100, 2018). "In this study, the ufmylation of RPL10 was confirmed in the tissues of PAAD patients and pancreatic cancer cell lines, and this modification was mediated by UFL1 at specific sites and cleaved by UFSP2." (PMID 37280198, 2023).
autism (9 papers, 2009 to 2025). Persistent deficits in social interaction and communication and interaction as well as a markedly restricted repertoire of activity and interest as well as repetitive patterns of behavior. "In the literature, RPL10 mutations have been reported to cause neurodevelopmental disorders with the clinical spectrum from autism to syndromic ID." (PMID 35436926, 2022). "Likewise, different case studies of neurodevelopmental disorders have revealed the involvement of the RPL10 gene mutations in autism in syndromic intellectual impairment." (PMID 35958988, 2022). "High expression of RPL10 was observed in mouse hippocampus, an important brain site for learning and memory, which are impaired in autism." (PMID 19166581, 2009). "To investigate whether RPL10 is involved in the pathogenesis of autism, we sequenced all RPL10 exons and quantified RPL10 mRNA level in patients with ASD and controls." (PMID 19166581, 2009). "Consequently, functionally altered RPL10 protein may contribute to cognitive malfunction, which is also observed in autism." (PMID 37807632, 2023).
viral infection (8 papers, 2009 to 2025). "The phosphorylation of RPL10 by its specific partner, the geminiviral nuclear shuttle protein-interacting kinase, redirects it to the nucleus to modulate viral infection." (PMID 36851755, 2023). "As the phosphorylated RPL10 translocates into the nucleus with the transcription factor LIMYB (L10-interacting MYB domain-containing protein), it forms RPL10-LIMYB complex that negatively regulate the virus infection by binding to the promoters of ribosomal protein gene and represses the expression." (PMID 34243802, 2021). "Phosphorylation of rpL10 by NIK promotes translocation of the ribosomal protein to the nucleus where it may function to mount a defense response that negatively impacts virus infection." (PMID 19492062, 2009). "Different RPs like RPL10, RPL13, RPL18, RPL24, and RPS6 are involved in viral infections of plants." (PMID 33995313, 2021).
breast carcinoma (6 papers, 2016 to 2023). "Deregulation of RPL15 expression enhances the translation of RPs and E2F pathway proteins to promote breast cancer metastasis, while mutations in RPs, including RPL10 and RPS15, also provide a potential oncogenic mechanism." (PMID 37264021, 2023). "Our lab recently identified the widely clinically used anti-depressant sertraline as a potent SHMT inhibitor that selectively inhibits proliferation of serine synthesis addicted breast cancer and RPL10 R98S T-ALL cells." (PMID 36932191, 2023). "Interestingly, Fang and Zhang find RPL10 to be a hub gene and potential biomarker for breast cancer." (PMID 35428183, 2022). "Furthermore, as evident from S7B–S7D Table, several late-type genes showed a significant, but opposite, association with prognosis in one or more cohorts compared to the initial analysis of breast cancer, exemplified by RPL10, EIF4B, GPBP1L1 in NSCLC and RPL3, RPS6 and STEAP1 in ovarian cancer." (PMID 27926932, 2016).
microcephaly (6 papers, 2020 to 2025). A congenital or acquired developmental disorder in which the circumference of the head is smaller than normal for the person's age and sex. "Brain defects have been found in patients carrying a mutated Rpl10 or Rps23, as they show an increased incidence in microcephaly, seizures, aphasia, ataxia, and intellectual disability." (PMID 35281111, 2022). "For instance, a loss of function mutation in RPL10/uL16 causes microcephaly and severely impaired cognitive function." (PMID 33565275, 2021). "In addition, RPL10 mutations have been linked to neurodevelopmental conditions, including autism spectrum disorders and microcephaly, and, indeed, translation is a process targeted in autism-associated disorders." (PMID 38254631, 2023).